STC1 (stanniocalcin 1)
Diseases named in the same sentence as STC1 in open-access papers (continued):
Sharing a sentence is not in itself a finding about the gene and the disease.
cancer (continued). "A literature search showed that many of these altered genes, such as IGF2, FAM83A, CEACAM5 and CEACAM6, STC1 and MSMP, play a role in PCa or other types of cancer." (PMID 31500347, 2019). "In contrast to STC1, STC2 has been consistently found to have an anti-apoptotic role in cancer cells." (PMID 24743310, 2014). "Both STC1 and STC2 are considered to be promising biomarkers, because their mRNA levels are elevated in the PB of cancer patients." (PMID 24743310, 2014). "The cancer cells are able to express a number of signals known as “do not eat me” signals through expression of CD47, CD24, PD-L1, the beta-2 microglobulin (β2M) subunit of MHC-I, stanniocalcin 1 (STC-1) and GD2 to evade the macrophage-mediated phagocytosis." (PMID 38566199, 2024). "STC1 can induce the adaptive response of human cancer cells to hypoxia by regulating hypoxia-inducible factor-1-α (HIF-1α), and is abnormally expressed in a variety of cancer types." (PMID 37576511, 2023). "Human cancer metastasis database (HCMDB) was analyzed that miR-20a-5p by targeting FGL2 and miR-139-5p by targeting STC1 could play a role mainly in liver metastatic CRC." (PMID 38036953, 2023). "STC1 expression was increased under hypoxia and STC1 was activated by HIF1 in cancer cells." (PMID 37988196, 2023). "Finally, we found that the expression of STC1, AKR1B1, and CD47 was increased along cancer invasion in clinical CRC samples using immunohistochemical staining." (PMID 36816947, 2023). "CAFs and STC1 could upregulate the expression of cancer stemness genes (NANOG, SOX2, and OCT4), and STC1-Ab treatment blocked the promoting effect of CAFs on the expression of stemness genes in HCC cells." (PMID 37004088, 2023). "Furthermore, we restored the expression of TWIST1 and STC1 in LNMAS overexpressed cells and determined their effects on cancer cells metastasis and macrophage phagocytosis, respectively." (PMID 35152264, 2022). "The negative regulation of REG4 by GATA6 was reversed to be positive from normal to cancer, the positive regulation of CA9 by GATA6 in normal tissue disappeared in cancer and the negative regulation of STC1 by GATA6 in normal stage was also disappeared in cancer." (PMID 35421923, 2022). "Taken together, we speculated STC1 augments the stem‐like traits of GBM cells and thus enhancing tumourigenicity and distal metastasis, since stem cell‐like properties of cancer cells play a major role in metastasis." (PMID 32468698, 2020). "Relative PAM, STC1, and HDAC4 expression were down-regulated, whereas CASP6, CHST6, SLC16A3, TPI1, KDELR3, VCAN, and CLDN9 were highly expressed in carcinoma tissues compared to the para-carcinoma tissues." (PMID 33424916, 2020). "Although there is growing evidence for the role of STC1 in human cancer, the clinical significance of STC1 overexpression in human cancer has not been established." (PMID 22200953, 2012). "We looked at the connections between STC1 and TMB and MSI to discover whether or not there is a connection between the activity of STC1 and mutations in certain forms of cancer." (PMID 39201771, 2024). "In this work, we investigated whether or not there was a connection between the expression of STC1 and the infiltration scores of common immune cell types in 33 different forms of cancer." (PMID 39201771, 2024). "We investigated the link between STC1 expression and many MMR genes to determine whether or not DNA methylation of STC1 directly influences the onset and progression of cancer." (PMID 39201771, 2024). "Regulation of STC1 expression involves a complex network of transcription factors and signal transduction pathways, implying its role as an intermediate modulator rather than a precise cancer determinant factor." (PMID 39186548, 2024).
cancer (continued). "As a hypoxia gene, STC1 is also an intracellular protein that can bind to mitochondrial receptors, increase mitochondrial oxidative phosphorylation (OXPHOS), and play an important role in epithelial-mesenchymal transition (EMT) and cancer stem cell (CSC) formation." (PMID 37576511, 2023). "Notably, our finding of the reduced expression of STC-1 being more frequent in obese and diabetic women also suggests that the substantial lack of the protein may be linked with other physiological metabolic risk factors that may not be evident in other cancer types." (PMID 34650342, 2021). "With substantial experimental evidence, STC1 was initially identified as an HIF-1 target gene in OvCa cell lines, playing a pivotal role in reprogramming ovarian tumor metabolism, unlike other cancers." (PMID 39186548, 2024). "Compared with non-TNBC cancers, the expression of STC1 in TNBC is higher, and the survival of TNBC patients with a high expression of STC1 is relatively poor." (PMID 34722511, 2021). "Besides VEGFA which was widely known and applied in anti-angiogenic therapy, in our pan-cancer analysis, some genes, like SPP1, STC1 and COL5A2, were not only highly expressed in most tumors, but also risk factors of prognosis." (PMID 36479101, 2022).
infection (4 papers, 2014 to 2025). The state of being infected such as from the introduction of a foreign agent such as serum, vaccine, antigenic substance or organism. "In our previous report, we showed that upon infection of primary lymphatic endothelial cells the levels of secreted STC1 protein increased by ELISA." (PMID 41342328, 2025). "Overall, cell culture infections corroborated observations in GI and skin KS that showed an increase in expression of STC1 and FLT4 with KSHV infection or reactivation." (PMID 37740179, 2023). "STC1 is expressed at higher levels in the human colon in response to infection with the protozoan parasite Entamoeba histolytica." (PMID 25297457, 2014). "The top upregulated genes in KSHV lytic and mixed infection spots are predicted to encode proteins that regulate angiogenesis including ADAMTS9, KDR and PGF, endothelial cell development including KDR and STC1, and cell-substrate adhesion, SPRY4, ITGA1, ADAMTS9, KDR, MMP12." (PMID 39386738, 2024). "This increased secreted STC1 protein could inhibit macrophage chemotaxis to infected cells and also may inhibit IL‐1β secretion from macrophages to inhibit a pro‐inflammatory response to infection." (PMID 41342328, 2025). "Taken together, our hypothetical model is that upon infection of endothelial cells with KSHV, endothelial cells secrete more STC1 protein." (PMID 41342328, 2025). "At 3-days post-infection, there was a mild reduction in expression of a KSHV latent gene, LANA, with siRNAs targeting STC1 and a lower virus input (MOI 0.25)." (PMID 37740179, 2023). "Repression of STC1 did not inhibit early viral entry based on measurement of a GFP reporter expressed by the KSHV virus or viral genomes per cell shortly after infection." (PMID 37740179, 2023).
cardiovascular disease (2 papers, 2025). "Diet-associated proteins (e.g., FSTL3, STC1, and CD302 antigen) significantly mediate risk associations for various chronic disorders, including cardiovascular diseases and chronic respiratory diseases." (PMID 40823023, 2025).
kidney (2 papers, 2021 to 2025). "Transgenic overexpression of STC1 in mice protects against ischemia-reperfusion kidney injury through suppressing superoxide generation." (PMID 41249792, 2025). "Hypoxic preconditioning induces STC1 expression in the heart, and brain, while transgenic overexpression of STC1 confers resistance to ischemia/reperfusion (I/R) kidney injury." (PMID 35098216, 2021).
reproductive diseases (1 paper, 2024). "Evidence proposed that the dysregulation of STC1, TIMP3, ITGA2, and INHBA is associated with the development of severe reproductive diseases." (PMID 38730500, 2024).
retinopathy (1 paper, 2020). "More recently, we demonstrated that STC-1 also has a role in development of the oxygen induced retinopathy stress response." (PMID 32365129, 2020).
STC1 also shares sentences with these, for which no sentence is quoted: Stroke (4 papers); adenocarcinoma (3); clear cell renal cell carcinoma (3); Crohn disease (3); glaucoma (3); renal cell carcinoma (3); cholangiocarcinoma (2); Hyperglycemia (2); medullary thyroid cancer (2); airway hyperresponsiveness (1); allergic asthma (1); angina (1); Ascites (1); benign tumors (1); Blindness (1); brain cancer (1); brain tumors (1); breast adenocarcinoma (1); calcific aortic valve disease (1); cervical squamous cell carcinoma (1); cervical tumor (1); chronic lymphocytic leukemia (1); Cirrhosis (1); COVID-19 (1); crescentic glomerulonephritis (1); deep venous thrombosis (1); diabetes mellitus type 2 (1); diffuse large B-cell lymphoma (1); Down syndrome (1); endocervical adenocarcinoma (1).
A further 33 diseases each share a sentence with STC1 in 1 paper.